CFAP47 (cilia and flagella associated protein 47)
Description:
Plays a role in flagellar formation and sperm motility.
Synonyms: CHDC2; CXorf22; CXorf30; CXorf59; FLJ36601; RP13-11B7.1; MGC34831; SPGF52; SPGFX3
Tractability: No criterion of Open Targets' tractability assessment is met for any kind of drug.
Gene: Protein-coding gene on chromosome X (35,919,734 to 36,385,317, forward strand). Ensembl gene ENSG00000165164.
Subcellular location: Cytoplasm, cytoskeleton, flagellum basal body
Gene Ontology:
Molecular function: protein binding
Biological process: sperm axoneme assembly; cilium assembly
Cellular component: sperm head-tail coupling apparatus; cilium
Gene-disease validity (ClinGen):
ClinGen rates the evidence that CFAP47 causes each of these diseases.
spermatogenic failure, X-linked, 3 (X-linked): Limited.
polycystic kidney disease (X-linked): Disputed. A usually autosomal dominant and less frequently autosomal recessive genetic disorder characterized by the presence of numerous cysts in the kidneys leading to end-stage renal failure.
Homologues: Orthologues: chimpanzee CFAP47 (99% identical). Paralogues in human: HYDIN (17% identical), DLEC1 (6% identical).
Diseases named in the same sentence as CFAP47 in open-access papers:
CFAP47 is named in the same sentence as 13 diseases in open-access papers, as found by Europe PMC text mining. Sharing a sentence is not in itself a finding about the gene and the disease. The quoted sentences say what the papers report.
infertile (4 papers, 2023 to 2025). "Subsequent genetic testing revealed a pathogenic large deletion at Xp21.1-p11.3, encompassing multiple OMIM Morbid genes, including DMD, Cilia- and flagella-associated protein (CFAP47 infertility), and XK (McLeod syndrome)." (PMID 40745660, 2025). "In the current study, we identified a novel homozygous mutation in CFAP47, which is located on the X chromosome, in two infertile patients." (PMID 37424856, 2023). "A previous study on an animal model reported a necessary role of Cfap47 in spermatogenesis in mice, and their patients with CFAP47 mutations were infertile, characterized by abnormal sperm motility and sperm flagellum morphology." (PMID 37424856, 2023). "In conclusion, our study identified a novel missense mutation in CFAP47 in two infertile male patients with various sperm morphology abnormalities, first revealing CFAP47 as a candidate causative gene of sperm multiple morphological abnormalities." (PMID 37424856, 2023).
male infertility (3 papers, 2022 to 2025). The inability of the male to effect fertilization of an ovum after a specified period of unprotected intercourse. "Our work highlighted a potential role of CFAP47 in sperm head and tail formation in humans, broadening the gene variant and phenotype spectrum of CFAP47 in male infertility." (PMID 37424856, 2023). "In conclusion, we report a novel CFAP47 variant in a PCD patient exhibiting male infertility, characteristic respiratory manifestations, and profound ultrastructural defects in both sperm flagella and respiratory cilia, notably the disruption of the conserved “9 + 2” microtubule arrangement." (PMID 40636384, 2025).
asthenozoospermia (1 paper, 2025). "Furthermore, genetic analysis of 320 Chinese men with asthenozoospermia identified previously unreported mutations in the CFAP47 gene in two patients." (PMID 40473901, 2025).
Azoospermia (1 paper, 2025). Absence of any measurable level of sperm,whereby spermatozoa cannot be observed even after centrifugation of the semen pellet. "For example, in this patient the first exons of CFAP47 are missing, and alterations in this gene have been associated with azoospermia." (PMID 41190063, 2025).
melanoma (1 paper, 2020). A malignant, usually aggressive tumor composed of atypical, neoplastic melanocytes. "Furthermore, the BMX and CFAP47 variants were found in homozygosity in a healthy control, thus being excluded, as familial melanoma susceptibility is consistent with autosomal dominant inheritance." (PMID 32276436, 2020).
oligoasthenoteratozoospermia (1 paper, 2023). A form of male infertility that is characterized by a combination of low number or oligozoospermia, poor motility or asthenozoospermia, and abnormal shape or teratozoospermia of sperms. "In this study, we identified a novel missense mutation (c.1414G>A; p.V472M) in CFAP47 in two unrelated patients with oligoasthenoteratozoospermia." (PMID 37424856, 2023).
polycystic kidney disease (1 paper, 2025). "Considering a recent study suggesting a role for CFAP47 in polycystic kidney disease, we examined the kidney histology of 10-week-old Cfap47-KO mice and found no apparent abnormalities." (PMID 40473901, 2025).
Sweeney-Cox syndrome (1 paper, 2022). "Some studies have suggested a link between CFAP47 and Sweeney-Cox syndrome, which is also characterized by significant facial dysplasia, including eyelid and facial bone defects and cleft lip formation." (PMID 36401472, 2022).
cancer (2 papers, 2017). A tumor composed of atypical neoplastic, often pleomorphic cells that invade other tissues. "The remaining variants were located in genes of largely unknown function such as (CFAP47, ITIH6 and ZNF630) or in cancer-associated genes namely; INTS6L90, 91 and SSX392." (PMID 28720891, 2017).
degenerative disease (1 paper, 2022). "As no specific or robust link between the ARHGAP4/CFAP47 genes and PHA has been identified to date, further research will be needed to understand whether they contribute to the incidence of this degenerative disease." (PMID 36401472, 2022).
CFAP47 also shares sentences with these, for which no sentence is quoted: McLeod syndrome (2 papers); primary ciliary dyskinesia (1); spermatogenic failure, X-linked, 3 (1).